KANSL1 (KAT8 regulatory NSL complex subunit 1)
Diseases named in the same sentence as KANSL1 in open-access papers (continued):
Sharing a sentence is not in itself a finding about the gene and the disease.
Uterine sarcomas (3 papers, 2024 to 2025). "In this study, we collected 9 uterine sarcomas with the KAT6B/A::KANSL1 fusion and analyzed their morphological features, together with a comprehensive analysis using immunohistochemistry, NGS (DNA and RNA), and FISH." (PMID 39627614, 2025). "Uterine sarcomas with KAT6B/A::KANSL1 fusion represent a new entity characterized by bland morphology, commonly with hybrid features of low-grade endometrial stromal sarcoma (LG-ESS) and tumors with smooth muscle differentiation." (PMID 39627614, 2025). "Given the distinct global DNA methylation and gene expression profile, we advocate for KAT6B/A::KANSL1 uterine tumours to be recognized as a distinct type of uterine sarcoma—KAT6B/A::KANSL1 uterine sarcomas." (PMID 39392508, 2024). "In conclusion, KAT6B/A::KANSL1 uterine sarcoma is a molecularly unique type of uterine tumour that should be recognized as a distinct entity." (PMID 39392508, 2024). "Perhaps surprisingly, in our study, KAT6B/A::KANSL1 uterine sarcomas with high-grade histological features exhibited a variable DNA methylation profile distinct from the core KAT6B/A::KANSL1 cluster tumours." (PMID 39392508, 2024). "In conclusion, KAT6B/A::KANSL1 uterine sarcoma is a molecularly unique tumour that should be recognized as a distinct entity." (PMID 39392508, 2024). "In the current study, KAT6B/A::KANSL1 uterine sarcomas falling into the core DNA methylation cluster were consistently histologically bland and showed no significant CNVs." (PMID 39392508, 2024). "This raises the question of whether secondary genomic alterations could play a role in high-grade transformation of KAT6B/A::KANSL1 uterine sarcomas, potentially correlating with an aggressive clinical course." (PMID 39392508, 2024).
asthma (2 papers, 2022 to 2023). "Most of the top eQTM genes have been implicated in lung disease for example PAX8; associated with bronchodilator response in children with asthma, ECHDC3 with obesity and asthma in children, LSP1 with acute lung inflammation, HLA‐DQB1 with asthma and total IgE, and KANSL1 with pulmonary function." (PMID 35344303, 2022).
congenital heart anomalies (2 papers, 2023 to 2024). "In 22q11.2DS patients, CNVs of the genes GPR98 (G-protein-coupled receptor 98), KANSL1 (KAT8 regulatory NSL complex subunit 1 gene) and SC2A3 (solute carrier family 2 facilitated glucose transporter member 3) have been described as risk factors for congenital heart anomalies." (PMID 38540380, 2024).
dementia (2 papers, 2023). Loss of intellectual abilities interfering with an individual's social and occupational functions. "However, only six of these genes emerged to be associated with AD in a certain way: HMGB1, which is related AD dementia according to ‘Disease Ontology’; KANSL1; BAZ2B; EHMT1; SIRT1; and CTBP1, which are associated with AD according to the literature data." (PMID 37175659, 2023).
leiomyosarcoma (2 papers, 2024 to 2025). An uncommon, aggressive malignant smooth muscle neoplasm, usually occurring in post-menopausal women. "RNA-sequencing-based gene expression profiling analysis showed a greater overlap of KAT6B::KANSL1 tumours with ESN and LGESS compared to leiomyomata and leiomyosarcoma." (PMID 39392508, 2024).
lung carcinoma (2 papers, 2024 to 2025).
medulloblastoma (2 papers, 2022 to 2023). A malignant, invasive embryonal neoplasm arising from the cerebellum. "This is supported by the fact that medulloblastoma samples expressing the ARL17A--KANSL1 circular fusion generally also express the KANSL1--ARL17A circular fusion, in fact, 11 out of 13 cases." (PMID 35804907, 2022). "The most abundant of the selected linear fusions in medulloblastoma is the KANSL1--ARL17A." (PMID 35804907, 2022). "Moreover, out of these 11 medulloblastoma samples, 9 also express the linear KANSL1--ARL17A fusion, suggesting that the mechanisms generating the KANSL1--ARL17A linear and circular fusions may be related." (PMID 35804907, 2022). "Of particular interest is the KANSL1--ARL17A/B fusion, as both linear and circular forms are observed in numerous medulloblastoma samples." (PMID 35804907, 2022). "For the last selected circular fusion in medulloblastoma, the ARL17B--KANSL1, it should be noted that the coding sequences of ARL17A (NM_001113738.2) and ARL17B (NM_001039083.5), including the exon 3 at the fusion, are identical." (PMID 35804907, 2022). "Importantly, the same exons of this linear fusion are also found in the most abundant selected circular fusions in medulloblastoma, namely the ARL17A--KANSL1 and the KANSL1--ARL17A." (PMID 35804907, 2022).
microcephaly (2 papers, 2014 to 2017). A congenital or acquired developmental disorder in which the circumference of the head is smaller than normal for the person's age and sex. "The literature reports show the effect of duplications in KANSL1 gene in individuals with development delay, microcephaly and mild dysmorphic features." (PMID 28496102, 2017).
Obesity (2 papers, 2021 to 2023). Accumulation of substantial excess body fat. "Besides, hypertension and diabetes are linked by CXCL8, HLA-B, and KANSL1; diabetes and obesity are linked by TRIM26 and MMP8; hypertension and obesity are linked by PLA2G7, FSTL3, STC2, and BCL2A1." (PMID 36685671, 2023). "In line with this hypothesis, genes PTK2B, KANSL1 and ADAM10 have been previously associated with obesity and BMI, while ABCA7 and ADAM10 have been associated with blood pressure." (PMID 34992629, 2021).
prostate carcinoma (2 papers, 2022 to 2024). A carcinoma that arises from epithelial cells of the prostate gland. "There were no previous descriptions for the fusions NAIP:OCLN, PDE1C:DNAJC6, KANSL1:ARL17B, FOXP2:CREM, and AHSA1:DLG3 in the context of prostate cancer." (PMID 35625354, 2022).
uterine tumors (2 papers, 2024 to 2025). "Moreover, KAT6B/A::KANSL1 uterine tumours have demonstrated malignant potential with a risk for metastasis/recurrence despite typically bland cytomorphology and often a circumscribed tumour border." (PMID 39392508, 2024). "Overall, studies to date have shown that KAT6B/A::KANSL1 uterine tumours can exhibit histologic and immunophenotypic features of both low-grade endometrial stromal and smooth muscle neoplasms." (PMID 39392508, 2024). "Herein we report the clinicopathologic and molecular features of a cohort of uterine tumours harbouring the KAT6B/A::KANSL1 gene fusion." (PMID 39392508, 2024). "In this study we investigated DNA methylation patterns and copy number variations (CNVs) in a series of uterine tumours harboring KAT6B/A::KANSL1 gene fusions in comparison to other mesenchymal neoplasms of the gynecological tract." (PMID 39392508, 2024). "It is worth noting that while a significant subset of KAT6B/A::KANSL1 uterine tumours exhibits focal sex cord differentiation, they displayed a methylation profile that was also distinct from UTROSCTs." (PMID 39392508, 2024). "The second series included 12 KAT6B/A::KANSL1 uterine tumours (including 12 primary and 4 recurrent tumours)." (PMID 39392508, 2024). "In this study, we employed global DNA methylation profiling and CNV analyses to gain insights into the classification of KAT6B/A::KANSL1 uterine tumour in comparison to other uterine mesenchymal tumours." (PMID 39392508, 2024). "For instance, if KAT6B/A::KANSL1 uterine tumours were to be considered a form of low-grade endometrial stromal neoplasm, the typically circumscribed tumour border would challenge our current diagnostic criteria that separate LGESS from ESN." (PMID 39392508, 2024). "As such, it is important to ascertain the nature and the precise classification of KAT6B/A::KANSL1 uterine tumours." (PMID 39392508, 2024). "In addition, KAT6B/A::KANSL1 uterine tumours lack evidence of Wnt/β-catenin pathway activation that is typically seen in LGESS." (PMID 39392508, 2024). "The major novel finding of our study is that KAT6B/A::KANSL1 uterine tumours are defined by a specific DNA methylation signature that is distinct from other uterine mesenchymal neoplasms, indicating they constitute a distinct type of uterine mesenchymal tumour." (PMID 39392508, 2024).
adenoid cystic carcinoma (1 paper, 2021). A malignant tumor arising from the epithelial cells. "KANSL1 gene which is mapped to pathways affected in adenoid cystic carcinoma was disrupted due to two large deletions of 644.6kb and 734.2kb identified in two unrelated patients, BC37 and BC39, respectively." (PMID 33503040, 2021).
amyotrophic lateral sclerosis (1 paper, 2024). Amyotrophic lateral sclerosis (ALS) is a neurodegenerative disease characterized by progressive muscular paralysis reflecting degeneration of motor neurons in the primary motor cortex, corticospinal tracts, brainstem and spinal cord. "As part of the nonspecific lethal complex, KANSL1 was previously identified as an essential gene for autophagy, a key machinery to maintain proteostasis, and dysregulation has been considered to play major roles in neurodegenerative diseases including amyotrophic lateral sclerosis and PD43–45." (PMID 38740892, 2024).
astroglioma (1 paper, 2022). "The effect of the KAT8 and KANSL1 KD on pUb(Ser65) was confirmed in WT SHSY5Y cells and the astroglioma H4 cell line, both of which are expressing endogenous levels of Parkin." (PMID 36074904, 2022).
bladder cancer (1 paper, 2021). "However, mutations in KANSL1 gene were also detected in multiple cancers including bladder cancer and germline copy number variation in this gene was also described in early colorectal cancer." (PMID 33503040, 2021).
breast tumor (1 paper, 2017). "KANSL1 has also been reported fused with ORMDL3 and LAYN in one breast tumor and with UNC45B in one lung tumor." (PMID 28423358, 2017).
dyslexia (1 paper, 2023). A learning disorder characterized by an impairment in processing written words. "Remarkably, among the BA genes we identified in our study, KANSL1 stands out—a gene previously reported to underlie dyslexia." (PMID 37561991, 2023).
encephalomyopathy (1 paper, 2023). "Pathophysiology associated with MOF and KANSL1 haploinsufficiency displays developmental and neurological impairments, which are also hallmarks of inherited mitochondrial diseases, including those of encephalomyopathy and Leigh syndrome associated with cytochrome c oxidase (COX) deficiency." (PMID 37813994, 2023).
endometrial stromal neoplasm (1 paper, 2024). "In these scenarios, molecular testing should ideally cover not only the KAT6B/A::KANSL1 fusion but also other relevant fusions associated with endometrial stromal tumors." (PMID 39392508, 2024).
hydronephrosis (1 paper, 2024). Collection of urine in the renal pelvis that results in dilatation of the renal pelvis and calyces. "Some of the CAKUT cases with associated malformations did reveal a pathogenic variant in WES (unilateral renal agenesis Hypomethylation C2; horseshoe kidney KMT2A; hydronephrosis FREM2, KANSL1; LUTO CHD7; renal hypoplasia GREBIL, POGZ)." (PMID 37535131, 2024).
lung adenocarcinoma (1 paper, 2025). A carcinoma that arises from the lung and is characterized by the presence of malignant glandular epithelial cells. "We explored the characteristic distribution of these genes in the tumor immune microenvironment and identified two A-ERGs, KDM6B and KANSL1, as potential diagnostic biomarkers for lung adenocarcinoma (LUAD)." (PMID 40832611, 2025).
memory impairment (1 paper, 2022). "After 24 h retention delay, Kansl1+/− mice displayed significant memory impairment compared to the wild type during the object recognition task." (PMID 35177641, 2022). "Next, we assessed the potential efficacy of 13-cis RA in improving learning and memory impairment in Kansl1+/− mice." (PMID 35177641, 2022).
mood disorder (1 paper, 2023). A cognitive disorder a disturbance in which the person's mood is hypothesized to be the main underlying feature. "The eQTLs associated with the index level mood disorders are associated with MAPT, KANSL1 and WNT3 transcript levels." (PMID 37336921, 2023).
smooth muscle tumours (1 paper, 2024). "Uterine mesenchymal tumours harboring KAT6B/A::KANSL1 gene fusions typically exhibit histological and immunophenotypic overlap with endometrial stromal and smooth muscle tumours." (PMID 39392508, 2024). "Given the incomplete current understanding of these neoplasms, we suggest that all uterine mesenchymal neoplasms with overlapping morphology and immunophenotype between endometrial stromal and smooth muscle neoplasms undergo molecular testing to identify a KAT6B/A::KANSL1 fusion." (PMID 39392508, 2024). "Furthermore, besides KAT6B/A::KANSL1 gene fusions, RNA sequencing did not identify prototypical gene fusions typically seen in HGESS or smooth muscle tumors in any of the outlier tumours." (PMID 39392508, 2024).
cancer (10 papers, 2019 to 2024). A tumor composed of atypical neoplastic, often pleomorphic cells that invade other tissues. "Among NSL complex members driving cancer traits, mutations in KANSL1 have been reported to promote malignancies." (PMID 31267707, 2019). "An earlier report identified KANSL1::ARL17 in diverse tumor samples and proposed that it may be a cancer predisposition germline fusion specific to Europeans." (PMID 37323575, 2023). "This was confirmed by our analysis since all candidate CNVs that we have identified and that were found to affect the cancer genes PMS2, APC2, POU5F1, KANSL1, DOCK8 and TMTC3 are part of this category." (PMID 33503040, 2021). "Contrasting expression pattern between the KANSL1-ARL17 fusion and its parent gene, KANSL1 in GBM compared to the normal brain warrants further investigation, as it suggests their potential role in cancer." (PMID 31992760, 2020). "All these findings support the implication of KANSL1 and PLEKHM1 in cancer which may explain the phenotype of our two patients." (PMID 33503040, 2021).
tumor (10 papers, 2015 to 2025). "Analysis of DNA methylation cluster assignments in relation to histological features revealed that while tumours in the core KAT6B/A::KANSL1 cluster were histologically bland, outlier tumours frequently exhibited “high-grade” morphological features." (PMID 39392508, 2024). "The median GI for the core KAT6B/A::KANSL1 cluster tumours was 17 (mean GI 51.7, range 3—266), in stark contrast to DNA methylation outlier tumours which showed a median GI of 272 (mean GI 906, range 8—3796)." (PMID 39392508, 2024). "Genome wide DNA methylation analysis of the study cohort identified a distinct cluster of tumours harbouring a KAT6B::KANSL1 gene fusion (“core KAT6B/A::KANSL1 cluster”), including 8 of 13 tumours analysed herein." (PMID 39392508, 2024). "Unsupervised hierarchical clustering and t-SNE analysis of DNA methylation data (Illumina EPIC array) identified a distinct cluster for 8/13 KAT6B/A::KANSL1 tumours (herein referred to as core cluster)." (PMID 39392508, 2024). "Twenty-eight tumours harbouring a KAT6B/A::KANSL1 gene fusion have been reported previously, and with the addition of cases we report in the current study, the total is 33 (11 of the cases we report have also been previously documented)." (PMID 39392508, 2024). "Interestingly, high expression of KANSL1 can lead to a shift in the mRNA expression of immune response gene sets from high to low levels, promoting tumor immune escape and thus facilitating tumor progression." (PMID 40832611, 2025). "The first series included 11 KAT6B::KANSL1 and 2 KAT6A::KANSL1 tumours." (PMID 39392508, 2024). "However, distinct differences in signaling pathways were noted between KAT6B::KANSL1 tumours and ESN/LGESS." (PMID 39392508, 2024). "Other novel tumor suppressor genes identified here include KANSL1, a scaffold protein for histone acetylation complexes, BMPR2, a receptor serine/threonine kinase for bone morphogenetic proteins, MAP2K7, involved in MAP-kinase signaling, and NIPBL, a member of the cohesin complex." (PMID 29056346, 2017). "Our study cohort consisted of 16 tumours harboring a KAT6B/A::KANSL1 gene fusion (KAT6B::KANSL1, n = 15; KAT6A::KANSL1, n = 1)." (PMID 39392508, 2024). "The ARL17A—KANSL1 fusion transcript has been identified in both normal and thymus and T cell lymphoblastic lymphoma tumor samples and is thought to be involved in tumor maintenance, rather than pathogenesis." (PMID 33946483, 2021). "RT-PCR with all four primer combinations, MORF-1234F/KANSL1–2969R1, MORF-1234F/ KANSL1–2900R1, MORF-1261F/KANSL1–2969R1, and MORF-1261F/KANSL1–2900R1, amplified cDNA fragments strongly suggesting the presence of a KAT6B-KANSL1 fusion transcript in the examined tumor (lanes 1–4)." (PMID 25621995, 2015). "CNV analysis did not identify significant alterations in the core KAT6B/A::KANSL1 cluster tumours." (PMID 39392508, 2024). "Interestingly, 5 tumours harboring a KAT6B/A::KANSL1 gene fusion, hereafter referred to as “outliers”, did not cluster with the core cluster." (PMID 39392508, 2024).
neurodegenerative disease (7 papers, 2022 to 2025). A disorder of the central nervous system characterized by gradual and progressive loss of neural tissue and neurologic function. "We demonstrate that the hemizygous deletion of the endogenous SVA_67 in CRISPR edited cell lines was associated with differential expression of several genes at the MAPT locus associated with neurodegenerative diseases including KANSL1, MAPT and LRRC37A." (PMID 37840928, 2023). "The association of KANSL1 disruptions with such a profound developmental disorder emphasizes the potential impact of KANSL1-related mechanisms in neurodegenerative diseases like PSP." (PMID 39154163, 2024). "In line with this hypothesis, it has been demonstrated that individuals with neurodegenerative diseases who carry the H1 haplotype exhibit decreased KANSL1 expression." (PMID 38254936, 2023). "The PD GWAS risk gene candidate KANSL1 is part of the non-specific lethal (NSL) complex and has been identified as an essential gene for autophagy, whereby impaired autophagy has been considered to be a potential cause for neurodegenerative diseases such as PD." (PMID 37840928, 2023).
neurodevelopmental disorder (5 papers, 2021 to 2026). A behavioral and cognitive disorder with onset during the developmental period that involves impaired or aberrant development of intellectual, motor, or social functions. "This may be an instrumental next step in responding to WDR5-associated neurodevelopmental disorders if future research goes in similar directions as ARID1B and KANSL1." (PMID 36743289, 2022).
genetic disorder (3 papers, 2022 to 2025). "Koolen‐de Vries syndrome (KdVS) is a rare genetic disorder caused by a de novo microdeletion in chromosomal region 17q21.31 encompassing KANSL1 or by a de novo intragenic pathogenic variant of KANSL1." (PMID 34665525, 2022). "Koolen‐de Vries syndrome (KdVS), also known as 17q21.31 microdeletion syndrome or KANSL1‐related intellectual disability (ID) syndrome (OMIM #610443), is a rare genetic disorder described for the first time in 2006." (PMID 34665525, 2022).